TMSB4X (thymosin beta 4 X-linked)
Diseases named in the same sentence as TMSB4X in open-access papers (continued):
Sharing a sentence is not in itself a finding about the gene and the disease.
cancer (37 papers, 2013 to 2026). A tumor composed of atypical neoplastic, often pleomorphic cells that invade other tissues. "TMSB4X (Thymosin beta 4 X-linked), which is upregulated in H295R-PM-Ptc+ cells, has been proposed to suppress E-cadherin expression, and to promote cancer cell growth and migration." (PMID 35631574, 2022). "Apart from these surface markers, one of the top differentially expressed genes is thymosin beta 4 (TMSB4X), which is associated with the stemness and differentiation of progenitor and cancer cells." (PMID 29540503, 2018). "It has been proposed that thymosin beta-4 × -linked (TMSB4X) may positively regulate the activity of ATP-synthase to transport proton from the intracellular to the extracellular space of cancer cells." (PMID 31811139, 2019). "Amongst the differentially expressed CGC genes, we observed and visualized several oncogenes that have been previously studied for their role in different cancers (e.g., TMSB4X and TNFAIP3)." (PMID 37355674, 2023). "The TMSB4X gene encodes for the thymosin beta 4 (Tβ4) protein, which is involved in hematopoietic stem cell function and mobilization, while the MMP-2 protein regulates cancer cell migration and invasion." (PMID 35955786, 2022). "The expression of TMSB10 and TMSB4X was positively correlated with the immune/stromal score in most cancer types." (PMID 36163046, 2022). "In terms of the role of TMSB4X in cancer, most studies have focused on its role in cancer cells, where in general, TMSB4X plays a pro-migratory role, drives EMT and positively associates with poor prognosis." (PMID 36169805, 2022). "Platelet markers that alter significantly in the presence of cancer have been identified as beta-2-microglobulin (B2M), pro-platelet basic protein (PPBP), thymosin beta 4 X-Linked (TMSB4X), and platelet factor 4 (PF4)." (PMID 35096878, 2021). "The TMSB4X, CNN3, TWF1, CORO1C and WASF2 genes encode cytoskeletal proteins related to actin filament dynamic regulation, and they are involved in cancer metastasis." (PMID 28159933, 2017). "Furthermore, a phosphorylation of TMSB4X S2 site was identified in the phosphoproteomic analysis, which was also found in studies of other cells and cancers." (PMID 36169805, 2022). "Furthermore, we also observed an increasing pattern of TMSB4X expression from primary cancer cells to LN-metastatic cells." (PMID 34663816, 2021). "We found that 30 of these genes which included Nckap1l, Ncf1, Pla2g15, Unc93b1, Lrrc33, Rgs10, Gmfg, Rbm25, C3ar1, Ccdc88b, Fam105a, Gng11, Phc1, Rasa4, Dag1, Tyrobp, Tmsb4x, Cfp, Prkd1, Gp49a, Trem2, C1qc, Lyz2, Igfbp7, Rab30, Cxcl16, Egfl7, Ube2r2, Pltp, and Cfb, showed a relation with cancer." (PMID 32812032, 2020). "Even in the presence of ADSC CM, the TMSB4X inhibition suppressed the growth of cancer cells." (PMID 31781249, 2019). "The epithelial-mesenchymal transition (EMT) mediated by TMSB4X facilitates cancer cell motility." (PMID 31781249, 2019). "Recent studies have shown that TMSB4X promotes metastasis in malignant tumors." (PMID 28159933, 2017). "Notably, genes such as TTC3, TMSB4X, MGST1, DNAJC3, and P4HB are closely linked to cancer cell proliferation and migration and may serve as key regulators of CC progression." (PMID 41315466, 2025). "In addition, thymosin-β4 (TMSB4X) and glutamate-ammonia ligase (GLUL), which were significantly upregulated by HBV genotype C and A infections, respectively, have been reported to be associated with other cancers." (PMID 34696350, 2021). "It has been reported that TMSB4X may enhance cancer metastasis." (PMID 28831179, 2017). "The expression of MISP, CHMP2B, IL-18, TMSB4X, and EFEMP1 proteins in carcinoma tissue was higher than that in para-carcinoma tissues." (PMID 38835670, 2024). "We found that AS-IV upregulated Atg12 and induced cancer cell autophagy through DCP1A and TMSB4X." (PMID 32265995, 2020).
cancer (continued). "Furthermore, the growth and invasion of cancer cells were decreased, even in the ADSC-conditioned medium treatment group (P < 0.05), by the inhibition of TMSB4X." (PMID 31781249, 2019).
infection (4 papers, 2024 to 2025). The state of being infected such as from the introduction of a foreign agent such as serum, vaccine, antigenic substance or organism. "Apart from immune system related genes, in infection-based analysis at 8 WPI, the genes TMSB4X was annotated with haemostasis (Reactome) and MSTRG.6303 with disease (Reactome) category pathways." (PMID 39019929, 2024).
kidney disease (4 papers, 2014 to 2024). "TMSB4X loss of function in the mouse severely disrupts heart development and promotes kidney disease." (PMID 33310787, 2020).
TMSB4X also shares sentences with these, for which no sentence is quoted: diabetic kidney disease (5 papers); pancreatic cancer (4); keratitis (3); Liver Fibrosis (3); dry eye (2); esophageal cancer (2); glioblastoma (2); kidney (2); medulloblastoma (2); myocardial ischemia (2); prostate carcinoma (2); rapidly progressive glomerulonephritis (2); Right ventricular hypertrophy (2); type 2 diabetes (2); adenoma (1); Alzheimer disease (1); amyotrophic lateral sclerosis (1); anemia (1); Arthritis (1); autism (1); brain injury (1); chronic myeloid leukemia (1); colitis (1); crescentic glomerulonephritis (1); embryonal tumors (1); ependymoma (1); fibrosis (1); gastrointestinal stromal tumor (1); glomerulosclerosis (1); gynecological tumor (1).
A further 24 diseases each share a sentence with TMSB4X in 1 paper.